CXCL11 (C-X-C motif chemokine ligand 11)
Diseases named in the same sentence as CXCL11 in open-access papers (continued):
Sharing a sentence is not in itself a finding about the gene and the disease.
tumor (continued). "The results suggested that the expression of CXCL11 in MM tissues increased compared with non-tumor tissues." (PMID 35568859, 2022). "The present study revealed the relationship between CXCL11 and tumor immune cells and found that CXCL11 significantly correlated with the infiltration levels of CD8+ T cells, T follicular helper cells, and MDSCs in most cancers." (PMID 35935945, 2022). "Results showed increased efficacy in CAR-T cells trafficking and tumor progression control of this combined strategy, as compared to VV.CXCL11 alone." (PMID 35211124, 2022). "The expression of CXCL9, CXCL10 and CXCL11 is positively correlated with the density of tumor infiltrating NK and T cells." (PMID 35033066, 2022). "Collectively, these findings establish that CXCL12 and CXCL11 additively or synergistically promote invasion of some tumor cells whereas in other tumor cells CXCL11 seems to suppress the stimulatory effects of CXCL12 on cell invasion." (PMID 36539774, 2022). "Together, these findings oppose a crucial role of MMP-9 and MMP-2 in the observed combined effects of CXCL12 and CXCL11 on tumor cell invasion." (PMID 36539774, 2022). "The correlations of CXCL11 with various parameters (such as stage and survival) are different for different tumor types." (PMID 35935945, 2022). "CXCL12 and CXCL11 were almost equally potent in inducing migration of the various tumor cells, resulting in a dose-dependent, maximal 2.5–3.5-fold increase of the migration index." (PMID 36539774, 2022). "One group designed an oncolytic virus overexpressing CXCL11 and proved increased frequency of tumor infiltrating lymphocytes in a murine tumor model." (PMID 35626062, 2022). "CXCR3 is a CXC chemokine receptor dominated by IFN-γ, which interacts with CXCL9, CXCL10, and CXCL11 to regulate tumor progression and cytokine secretion." (PMID 35571062, 2022). "CXCL12 and CXCL11 affect tumor cell functions by either binding their prime receptors, CXCR4 and CXCR3, respectively, and/or CXCR7 as a common second chemokine receptor." (PMID 36539774, 2022). "We assessed the growth of tumor activity and found that the size of tumors in the sh-CXCL11 group were substantially smaller than tumors in the sh-control group." (PMID 35568859, 2022). "The intratumoral heterogeneity was also explored using the Tumor Purity value, with which CXCL11, ERAP2, FYN, GH1, MAP3K14, and SEMA6C were found negatively correlated, while the rest were positively correlated." (PMID 36428747, 2022). "After establishing a subcutaneous xenotransplanted tumor model of CAFs plus HCC cells in mice, we set out to validate the effects of LINC00152 knockdown and CXCL11 overexpression on tumor growth in vivo." (PMID 36435866, 2022). "In OC, downregulation of CXCL11 restrained angiogenesis and tumor growth, however, in our study, CXCL11 predicted better prognosis, contrary to previous studies, so further studies were still needed to explore the mechanism." (PMID 35812403, 2022). "The few available studies so far demonstrated that a combination of CXCL12 and CXCL11 either potentiated or diminished tumor cell migration when compared to single chemokines." (PMID 36539774, 2022). "CXCL11 was observed to be expressed mainly in the cytoplasm and locally in the cell membrane of tumor cells." (PMID 33547412, 2021). "Further comprehensive analysis of the tumor immune microenvironment (TIME) revealed that CXCL11 expression signature was closely correlated with cytotoxic cells, neoantigen load and immune checkpoint blockade (ICB)." (PMID 34047476, 2021). "High tumor expression of c-Met and high basal serum levels of HGF, IL-6, CXCL11 and CXCL10 were significantly associated with reduced PFS and/or OS." (PMID 34200459, 2021). "In orthotopic tumor tissues, CXCL11 protein expression was dramatically higher in the Huh-7 cells + CAFs and Huh-7 cells + CAFs (sh-NC) groups compared with those in the Huh-7 cells + CAFs and Huh-7 cells + CAFs (sh-NC) groups." (PMID 33707417, 2021).
tumor (continued). "To investigate the in vivo effects of CAFs-derived CXCL11, we first generated orthotopic implantation tumor models in mice." (PMID 33707417, 2021). "While little is known about CXCL4 expression in GBM, CXCL9, CXCL10 and CXCL11 are expressed by tumor cells." (PMID 34203660, 2021). "CXCL9, CXCL10 and CXCL11 are chemoattractant cytokines for anti-tumor leukocytes that express CXCR3, such as effector T cells." (PMID 33446805, 2021). "To understand the underlying mechanism of CXCL11 in COAD, we investigated the associations of CXCL11 with the tumor immune microenvironment." (PMID 33777950, 2021). "First, we verified the upregulated protein expression of CXCL11 in tumor tissue compared to adjacent normal tissue by IHC staining." (PMID 33777950, 2021). "The expression of CXCL11 in the cytoplasm of tumor cells was demonstrated to be significantly correlated with the response to ICIs (P = 0.003)." (PMID 33547412, 2021). "A study on BALB/c mice bearing CT26.WT cell xenografts showed enhanced tumor growth and invasiveness after peritumoral application of CXCL11 to the TME." (PMID 33777950, 2021). "Our results showed that the expression of CXCL9, CXCL10, and CXCL11 was significantly higher in tumor than in adjacent normal tissues in 136 CRC patients." (PMID 34539647, 2021). "In this cohort, tumor patients with high CXCL11 expression exhibited markedly improved clinical benefits and significantly prolonged survival." (PMID 34047476, 2021). "Nevertheless, PD-L1 blockade combined with an oncolytic vaccinia virus expressing CXCL11 in murine tumor models was shown to significantly reduce tumor burden and improve prognosis." (PMID 33777950, 2021). "In contrast, CXCR3-dependent anti-tumor activity has been found in vitro and in vivo and CXCL11 through the CXCR3 can attract CD8+ cytotoxic T cells to inhibit tumor growth." (PMID 33407095, 2021). "In this study, we found upregulation of CXCL11 expression in COAD tumor tissues compared with normal tissues in the TCGA, GEO single-cell RNA-seq datasets and YJSHC cohort, and that elevated CXCL11 had independent prognostic value in COAD." (PMID 33777950, 2021). "The expression of CXCL9, CXCL10, and CXCL11 except for CCL5 was significantly higher in the tumor compared with the adjacent normal tissues (p = 0.0707, p = 0.0001, p < 0.0001, and p = 0.4207)." (PMID 34539647, 2021). "CXCL11 protein expression was confirmed in our cohort by immunohistochemistry (IHC), and the effect of CXCL11 on the tumor immune microenvironment was also evaluated." (PMID 33777950, 2021). "Along the same lines, other studies have linked increase of cytokines, like CXCL9, CXCL10, CXCL11, and CXCL19, under ICIs as a sign of enhanced general immune reactivity with both subsequent tumor responses and development of irAE in NSCLC." (PMID 34268127, 2021). "As shown in serial sections, tumor with a high abundance of CXCL11+ cell infiltration tended to have a high abundance of intratumoral CD8+ T cell and CD56+ NK cell infiltration, which was associated with antitumor immunity." (PMID 33777950, 2021). "Novel strategies, such as the transfection of tumor migratory chemokines and their receptors, CXCL11 and CCR2, have been utilized to enhance the tumor localization of CAR-T cells with significant success." (PMID 33918403, 2021). "First, we evaluated the distribution of CXCL11 in tumor tissue across all TCGA cancers in TIMER and found that CXCL11 expression was significantly upregulated in the majority of tumors, including COAD and READ." (PMID 33777950, 2021). "CXCL11 expression was upregulated in the tumor samples and it was significantly higher in PC tissues than in adjacent non-neoplastic tissues." (PMID 32341359, 2020). "On the other hand, CXCL9 and CXCL11, secreted by M1 macrophages, promote a Th1-type response and stimulate tumor-infiltrating cytotoxic T cells." (PMID 33238581, 2020).
tumor (continued). "CXCL11 and CXCL13 are associated with CD8+ T cell and B cell infiltration, which act as a protective factor inhibiting tumor." (PMID 32208363, 2020). "In summary, our study shows that miR-548t-5p, which is regulated by YY1, is significantly downregulated in PC and suppresses tumor growth and metastasis by targeting CXCL11." (PMID 32341359, 2020). "The expression levels of CXCL9, CXCL10, CXCL11, CXCL12, and CXCL14 were associated with various tumor stages in HNSCC." (PMID 33489879, 2020). "CXCL11 arming was found to attract higher numbers of tumor-specific CD8+ T cells compared to parental virus; consequently, higher therapeutic benefits were achieved with the CXCL11-encoding virus." (PMID 32604787, 2020). "Cancer cells can produce CXCL11 by autocrine or release CXCL11 via regulating tumour stromal cells in the microenvironment." (PMID 33287740, 2020). "CXCL9, CXCL10, and CXCL11 in TME were primarily secreted by tumor cells, monocytes, fibroblasts, and endothelial cells in response to IFN-γ." (PMID 32685487, 2020). "We analyzed the tumors and adjacent normal tissues for the presence of specific chemokines, and found that CXCL11 was mostly significantly decreased in tumor tissues (n = 77)." (PMID 30744691, 2019). "We found that DOC upregulated the expression of chemokine receptor ligand CXCL11 in tumor microenvironment and subsequently enhanced CD8+ T cell recruitment." (PMID 30744691, 2019). "This study demonstrated a positive correlation of CXCL9, CXCL10, and CXCL11 mRNA expression with the density of tumor-infiltrating T and NK cells." (PMID 30873179, 2019). "CXCL11 and HMGB1 protein levels were assessed in 100 tumor tissues by IHC, and analyzed for associations with clinical outcomes." (PMID 30744691, 2019). "In this study, we found that DOC upregulated CXCL11 in the tumor microenvironment and subsequently enhanced the recruitment of CD8+ T cells." (PMID 30744691, 2019). "On the other hand, a study on human colon adenocarcinoma showed enhanced tumor growth and invasiveness after injection of CXCL11 to the TME." (PMID 31216755, 2019). "We found that CXCL11 was mostly significantly decreased in tumor tissues, and identified nine patients with increased CXCL11 expression in tumor tissues compared to adjacent normal tissue samples." (PMID 30744691, 2019). "In this study, we found that the expression of CCL5, CXCL9, and CXCL11 was increased in tumor cells after irradiation." (PMID 31921127, 2019). "Since IFN-I is known to induce the expression of lymphocyte-recruiting chemokines such as CXCL9, CXCL10, and CXCL11, we measured the mRNA expression level of these chemokines in the tumor-containing lungs at 21 d.p.i." (PMID 31049360, 2019). "We performed a comparative analysis of CXCL11 in tumor versus adjacent normal tissue from patients with NSCLC, and identified nine patients with increased CXCL11 expression in tumor tissues compared to adjacent normal tissue samples." (PMID 30744691, 2019). "Excitingly, the authors also observed a greater presence of chemokines like CXCL11 in the tumor as well as antigen-specific killing by T cells." (PMID 30804938, 2019). "To understand how DOC stimulated the production of CXCL11, we used qRT-PCR to assess RNA levels of several cytokines in tumor cells after treatment with DOC." (PMID 30744691, 2019). "It has also been described that the repression of CXCL11 in CRC tissues diminished the tumor cell growth and metastasis." (PMID 31216755, 2019). "Our study identifies the CXCR7/CXCL11 axis as a critical component of OC tumor stroma activation with a role of estrogen in promoting such transition, thereby determining the acquisition of metastatic phenotype and the fate of patients with OC." (PMID 30051594, 2018). "Melanoma and pancreatic tumors treated with this combination therapy express an immune stimulatory SASP, most significantly CCL5, IFN-β, and CXCL11, to promote dendritic cell proliferation and enhanced cytotoxic lymphocyte anti-tumor activity." (PMID 29868482, 2018).
tumor (continued). "The combination of CXCL11-expressing OV plus α-PD-L1 significantly reduced tumour burden and achieved better survival compared to monotherapy." (PMID 28345650, 2017). "CXCL11 immunoreactivity was mainly detected at the basolateral surface of tumor cells, but reactivity was also observable in the stroma, in accordance with in vitro results." (PMID 29163806, 2017). "We found CXCL9 and CXCL10 expressing on tumor cells and stromal cells, and CXCL11 expressing strongly on stromal cells and weakly on tumor cells." (PMID 26910919, 2016). "CXCL11 can also bind to a different variant of CXCR3 receptor and mediate inhibition of endothelial cells and thus tumor angiogenesis." (PMID 26956047, 2016). "For example, local administration of CXCL11 in a mouse model of colorectal cancer enhanced tumor growth." (PMID 26347749, 2015). "In breast cancer, NK cells take advantage of their own production of IFN-γ to enhance the secretion of chemokines CXCL9, CXCL10, and CXCL11 by tumor cells, which in turn accelerate the infiltration of CXCR3 expressing NK cells into the tumor site." (PMID 25110692, 2014). "Primary tumor cells can produce a cytokine lymphotoxin, which stimulates the release of a chemokine CXCL11 from the neighboring stromal fibroblasts though a lymphotoxin beta receptor - NFκB signaling dependent mechanism." (PMID 24384839, 2013). "CXCL11 has angiostatic properties and promotes the migration of cytotoxic T lymphocytes toward tumors triggering tumor cell apoptosis while CXCL13, a B cell attracting chemokine is responsible for the development of secondary lymphoid tissue in the gut." (PMID 24312117, 2013). "RNA and protein levels of two known ligands of CXCR3, CXCL10/IP10 and CXCL11/IP9 were down-regulated in the tumor lines." (PMID 22236567, 2012). "In our earlier study, we have shown that migration of CTL derived from a CRC patient towards autologous tumor cells was mediated by CXCR3 expressed by the T cells, and CXCL11 chemokine secreted by the autologous tumor cells." (PMID 21450101, 2011). "Finally, in vivo experiments further validated the tumor-promoting role of CAFs-secreted CXCL11 in NPC." (PMID 42077068, 2026). "Overall, we delineated cell–cell interaction landscape of tumor cells and immune cells and revealed that Plac1+ tumor cells recruited CD4+ T cells through the CXCL11/CXCR3 axis and then induced Treg differentiation through PVR/TIGIT to shape the immunosuppressive TME of HNSCC." (PMID 40056047, 2025). "Furthermore, direct delivery of CXCL11 to the tumor site via the oncolytic vaccinia virus was found to be more efficient in inducing cancer cell killing in vivo than the secretion of CXCL11 by CAR-T cells themselves." (PMID 41024300, 2025). "CXCL11 produced by MM cells increases the number of M2 macrophages in the bone marrow microenvironment, promoting macrophage polarization toward an immunosuppressive M2 phenotype that supports tumor growth." (PMID 40940985, 2025). "However, patients with high CXCL11 expression exhibited longer survival, potentially due to its role in promoting anti-tumor immunity." (PMID 41357585, 2025). "This suggests that butyrate may facilitate NK cell trafficking to tumor sites by modulating CXCL11 expression." (PMID 40576244, 2025). "Additionally, CXCL11/CXCL12–ACKR3 interactions in apCAFs promoted tumor progression in non‐responders." (PMID 40843133, 2025). "Moreover, our transcriptomic data further revealed that lacidipine regulated multiple immune‐related genes, significantly upregulating “hot” tumor‐related genes such as CCL5, CD274, CXCL10, and CXCL11, while downregulating the “cold” tumor‐related gene CCL2." (PMID 39585774, 2025). "Similarly, arming vaccinia virus with CXCL11—a CXCR3 ligand—was found to improve the migration of transferred effector cells into the tumor." (PMID 41294877, 2025).
tumor (continued). "In addition, our research illustrated that butyrate stimulated the CXCL11 secretion from tumor cells, thus potentially enhancing NK cell migration and subsequently inducing potent anti-tumor effects." (PMID 40576244, 2025). "Taken together, these findings suggest that butyrate might mediate tumor suppression by inducing CXCL11 secretion, thus enhancing NK cell recruitment to tumor sites and inhibiting tumor cell growth." (PMID 40576244, 2025). "We postulated that CXCL11 may play a crucial role in butyrate-mediated tumor suppression in a hepatic tumors mouse model." (PMID 40576244, 2025). "Therefore, APOC1+ TAMs and CXCL11+ TAMs potentially suppress anti-tumor immunity by inducing T cell dysfunction, exhaustion or even apoptosis through LGALS9 − HAVCR2 pair." (PMID 39232806, 2024). "The discrepancy in the function of CXCL11 on macrophage polarization between PF and the TME may be due to differences in the properties of normal and tumor-associated macrophages in terms of surface marker expression, secreted factors, and functions." (PMID 39548525, 2024). "CXCR3, a receptor for the chemokine CXCL11, demonstrates strong anti-tumor activity in vivo." (PMID 39139574, 2024). "However, SFRP2, SPINK1, CXCL11, CXCL13, and CXCL10 exhibited gene copy loss in certain tumor populations." (PMID 38577604, 2024). "In addition, the knockdown of BANCR downregulated the chemokine CXCL11, and when CXCL11 was reintroduced, tumor cell migration was restored." (PMID 39408810, 2024). "The tumor growth molecular mechanism of CXCL11 needs further study." (PMID 38745115, 2024). "CXCL11 and B cell marker B220 positively correlated with a better clinical outcome of breast cancer, suggesting tumor-associated neutrophils can suppress CD8+ T cells by blocking another protective immune branch acting around the tumor sites." (PMID 38786066, 2024). "CXCL11 or CXCL12 can alternatively bind CXCR7 which promotes tumor development." (PMID 38786066, 2024). "Furthermore, CXCL11 is involved in tumor lymphatic cross talk and the regualtion of checkpoint molecule PD-L1 (CD274) in cancer tissues." (PMID 38609887, 2024). "Notably, CXCL11+ TAMs with high expression level of interferon genes play a dual role in tumor immunity." (PMID 39232806, 2024). "Studies show that intratumoral administration of a CXCL11-armed tumour selective vaccinia OV increases tumour-specific CTLs and granzyme B production, while reducing immunosuppressive cytokines in the TME of a syngeneic mouse mesothelioma model, leading to enhanced cytotoxic activities of CTLs." (PMID 39450176, 2024). "Notably, CXCL11 is positively associated with the infiltration of CD8+ T cells and follicular helper T cells in the tumor microenvironment, indicating its involvement in immune cell infiltration and potential impact on immunotherapy efficacy." (PMID 38791448, 2024). "In general, CXCR3 is highly expressed on the surface of NK cells, and it drives NK cell-specific chemotaxis toward the CXCR3 ligands CXCL9, CXCL10 and CXCL11, which are secreted by tumor cells into TME and usually expressed at relative low levels in homeostatic condition." (PMID 38264648, 2023). "CXCL11 is a potent chemokine that recruits T-cells into the tumor microenvironment." (PMID 38136398, 2023). "Moreover, chemotactic cytokines such as IL-6 or CXCL11 secreted by senescent endothelial cells can directly stimulate proliferation and aggressiveness of tumor cells." (PMID 36978029, 2023). "Interestingly, we also found that the abnormal expression of CXCL9, CXCL11, and CXCL13 is significantly associated to tumor stage, indicating that these CXCLs are closely related to tumor invasion and metastasis." (PMID 36798787, 2023). "pEMT-like tumor cells were prone to recruit PCs by secreting cytokines such as CXCL10 or CXCL11." (PMID 37138324, 2023). "This study demonstrated that local release of CXCL11 induces systemic tumor immunity." (PMID 37547756, 2023).